ENSG00000256407 (novel transcript)
Gene: Protein-coding gene on chromosome 1 (54,132,686 to 54,200,073, reverse strand). Ensembl gene ENSG00000256407.
Genetic constraint (gnomAD): Missense variants: 100 observed, 114.93 expected, observed/expected ratio (o/e) 0.87, 90% interval 0.74 to 1.03. Synonymous variants: 34 observed, 41.13 expected, observed/expected ratio (o/e) 0.83, 90% interval 0.63 to 1.1.